COX4I1 (cytochrome c oxidase subunit 4I1)
Diseases named in the same sentence as COX4I1 in open-access papers:
COX4I1 is named in the same sentence as 87 diseases in open-access papers, as found by Europe PMC text mining. Sharing a sentence is not in itself a finding about the gene and the disease. The quoted sentences say what the papers report.
glioma (10 papers, 2015 to 2025). A benign or malignant brain and spinal cord tumor that arises from glial cells (astrocytes, oligodendrocytes, ependymal cells). "In contrast, the isoform switch from COX4i2 to COX4i1 in glioma cells was associated with increased COX activity and respiration." (PMID 32075102, 2020). "In addition, a significant direct correlation between the expression of COX4I1 and BMI1 was observed in human tissue from primary gliomas at the mRNA and protein levels." (PMID 25726526, 2015).
glioblastoma (6 papers, 2015 to 2025). The most malignant astrocytic tumor (WHO grade IV). "Moreover, increased expression of COX4I1 is correlated with shorter progression-free and OS in patients with glioblastoma multiforme (GBM)." (PMID 35493303, 2022).
COVID-19 (5 papers, 2020 to 2026). A disease caused by infection with severe acute respiratory syndrome coronavirus 2. "The Mann–Whitney U test showed significantly decreased levels in symptomatic COVID-19 compared to controls (NDUFA9: p = 0.04; SDHA: p = 0.01; COX4I1: p = 0.01)." (PMID 34679654, 2021). "Similarly, COVID-19 symptomatic cases also showed significantly lower expression levels of these genes compared to controls, together with a decrease in genes belonging to the mitochondrial respiratory chain subunits (NDUFA9, SDHA, COX4I1) and to mitochondrial dynamics (DNM1L, FIS1)." (PMID 34679654, 2021).
Obesity (5 papers, 2016 to 2023). Accumulation of substantial excess body fat. "We found that low COX4I1 and low COX10 in monocytes and adipose tissues of patients and in adipose tissues of double-knock-out mice were associated with obesity and type 2 diabetes." (PMID 28122051, 2017). "We previously showed that decrease in nucleus encoded COX4I1 and COX10 depended on obesity and insulin resistance and diabetes." (PMID 28122051, 2017). "Additionally, COX4I1 downregulation in obesity decreases protection against mitochondrial oxidative stress and increases metabolism, which may eventually result in type 2 diabetes." (PMID 37375588, 2023).
colorectal cancer (4 papers, 2021 to 2024). A primary or metastatic malignant neoplasm that affects the colon or rectum. "Furthermore, NDUFB8, UQCRC2, COX4I1, and ATP5A low levels were associated with lower relapse-free survival in colorectal cancer patients." (PMID 39595536, 2024).
Hypertension (3 papers, 2018 to 2022). The presence of chronic increased pressure in the systemic arterial system. "Here, in the myocardium of the hypertension-induced HFpEF, we also observed the increased expression of PGC-1a after CANA treatment, which was consistent with the increased expression of the mitochondrial membrane respiratory chain component protein subunit Ndufb4, COX2, Cox4i1, Cox5b, and Cox6a1." (PMID 35370704, 2022).
Sepsis (3 papers, 2019 to 2025). Sepsis is defined as life-threatening organ dysfunction caused by a dysregulated host response to infection. "Using single‐nucleus RNA sequencing data from an in vivo mouse model of sepsis, tissue‐independent down‐regulation and tissue‐specific differences of serine and energy‐related genes including key module roles for the mitochondria‐linked genes, Cox4i1, Cox8a, and Ndufa4 are identified." (PMID 40411399, 2025).
cardiac hypertrophy (2 papers, 2021 to 2024). "Network analysis mapping protein–protein interactions and synergistic actions of AR using multi-component networks reveal drug targets such as ACADM, COX4I1, COX6B1, HBB, MYH14, and SLC25A4, as potential pharmacological co-targets for cardiac hypertrophy." (PMID 33589646, 2021).
Fanconi anemia (2 papers, 2021 to 2022). Fanconi anemia (FA) is a hereditary DNA repair disorder characterized by progressive pancytopenia with bone marrow failure, variable congenital malformations and predisposition to develop hematological or solid tumors. "In 2017, we reported a novel form of isolated COX deficiency caused by a K101N variant of the COX4I1 gene encoding COX4-1 in a patient presenting with Fanconi anemia-like features, short stature and mild dysmorphism, while all the known Fanconi anemia (FA) gene sequences were intact." (PMID 33672589, 2021). "We previously reported a patient with primary COX deficiency due to a pathogenic variant in COX4I1 (encoding the common isoform of COX subunit 4, COX4-1), who presented with bone marrow failure, genomic instability, and short stature, mimicking Fanconi anemia (FA)." (PMID 35456968, 2022).
leukemia (2 papers, 2022 to 2025). A malignant (clonal) hematologic disorder, involving hematopoietic stem cells and characterized by the presence of primitive or atypical myeloid or lymphoid cells in the bone marrow and the blood. "Our investigation pinpointed cytochrome c oxidase subunit 4 isoform 1 (COX4I1), a nuclear encoded mitochondrial protein, as crucial for leukemia survival." (PMID 39716856, 2025). "Through these functional genetic approaches, we uncovered the pivotal role of COX4I1, a mitochondrial protein encoded by the nuclear genome, in leukemia progression." (PMID 39716856, 2025). "Employing the MAGeCK algorithm, this focused CRISPR screen unveiled COX4I1 (encoding Cytochrome c oxidase subunit 4 isoform 1) as a top essential gene in leukemia cells, alongside five previously reported leukemia essential genes (MYC, RPS6, CCND3, GAB2, and AURKB)." (PMID 39716856, 2025). "This “human‐in‐mouse” xenograft leukemia model revealed a significant reduction in leukemia burden upon COX4I1 depletion (as detected by non‐invasive bioluminescence in vivo imaging)." (PMID 39716856, 2025). "The impact of COX4I1 knockout on leukemia cell survival prompted us to explore its potential combinatorial benefits with standard AML regimens such as azacitidine, cytarabine, and venetoclax." (PMID 39716856, 2025). "CRISPR gene tiling scans, coupled with mitochondrial proteomics, dissected critical regions within COX4I1 essential for leukemia cell survival, providing detailed insights into the mitochondrial Complex IV assembly network." (PMID 39716856, 2025). "Collectively, our study suggests the potential to enhance venetoclax's anti‐leukemia efficacy through combinatorial targeting of COX4I1." (PMID 39716856, 2025). "CRISPR depletion of COX4I1 also resulted in reduced colony‐forming capacity of the leukemia cells, highlighting the requirement of COX4I1 in leukemia cell proliferation." (PMID 39716856, 2025). "Functionally, ectopic expression of wild‐type (WT) COX4I1 cDNA, but not the P1‐deleted (ΔP1) or P2‐deleted (ΔP2) variants, rescued impaired cellular survival and mitochondrial respiration in COX4I1 knockout leukemia cells." (PMID 39716856, 2025). "In this study, we conducted a series of CRISPR genetic screens in leukemia cells, including a cell signaling pathway‐focused screen and a high‐density COX4I1 CRISPR tiling screen." (PMID 39716856, 2025). "To assess the impact of targeting COX4I1 on the maintenance of human leukemia, we transduced a Molm13‐Cas9+/Luc+ human acute myeloid leukemia (AML) model with sgCtrl and sgCOX4I1." (PMID 39716856, 2025). "We observed that similar to CRISPR inhibition of COX4I1, chlorpromazine treatment potentiates the efficacy of venetoclax in suppressing leukemia cell survival." (PMID 39716856, 2025). "However, leukemia cells exhibited nearly a 10 fold higher sensitivity to venetoclax (also known as ABT‐199) when COX4I1 was depleted." (PMID 39716856, 2025). "Depletion of COX4I1 hindered leukemia cell proliferation and impacted in vivo AML progression." (PMID 39716856, 2025). "Furthermore, COX4I1 depletion or pharmacological inhibition of Complex IV (using chlorpromazine) synergized with venetoclax, providing a promising avenue for improved leukemia therapy." (PMID 39716856, 2025). "Targeting COX4I1 in combination with venetoclax shows promise for enhancing leukemia therapy." (PMID 39716856, 2025). "Importantly, CRISPR depletion of COX4I1 delayed leukemia onset in recipient mice, providing proof‐of‐concept evidence of targeting COX4I1 in vivo to disrupt the progression of human AML." (PMID 39716856, 2025). "Following the refinement of CRISPR results using a local smoothen model, our CRISPR tiling scan unveiled the pivotal roles of two regions, P1 (K67–S74 in the matrix domain) and P2 (K135–K169 comprising the intermembrane space domain) within COX4I1, that is critical for leukemia cell survival." (PMID 39716856, 2025).
leukemia (continued). "To evaluate the role of COX4I1 in cellular energy metabolism, we quantified levels of AMP, ADP, and ATP in Molm13 leukemia cells using mass spectrometry and observed a pronounced reduction of ATP‐to‐AMP ratio upon COX4I1 depletion." (PMID 39716856, 2025). "To validate the screen results, we transduced Cas9‐expressing leukemia cells (including Molm13, MV4‐11, and THP‐1) with sgRNAs targeting COX4I1 (sgCOX4I1) and non‐essential sequences (sgCtrl)." (PMID 39716856, 2025). "As CRISPR targeting COX4I1 increased the sensitivity of AML cells to venetoclax, we further sought to investigate the capacity of chlorpromazine to potentiate the anti‐leukemia effects of venetoclax." (PMID 39716856, 2025).
skin cancer (2 papers, 2014 to 2022). "Also, the COX4I1 gene is downregulted in tumors with 16q loss and previous studies have shown that this gene is downregulated in skin cancer." (PMID 24509483, 2014).
acute myeloid leukemia (1 paper, 2025). Acute myeloid leukemia (AML) is a group of neoplasms arising from precursor cells committed to the myeloid cell-line differentiation. "Here, a cell signaling‐focused CRISPR screen identified cytochrome c oxidase subunit 4 isoform 1 (COX4I1) as a novel vulnerability in acute myeloid leukemia (AML)." (PMID 39716856, 2025). "Using a cell signaling‐focused CRISPR screen, this study revealed COX4I1 as a new vulnerability in acute myeloid leukemia (AML) via maintaining mitochondrial ultrastructure and oxidative phosphorylation." (PMID 39716856, 2025).
autoimmune disease (1 paper, 2017). A disorder resulting from loss of function or tissue destruction of an organ or multiple organs, arising from humoral or cellular immune responses of the individual to their own tissue constituents. "EMC8 and COX4I1 RNA expression was relatively unchanged by activation, whereas IRF8 expression was upregulated 97-fold, coincident with the induction of 16 intergenic IRF8 PIRs, four of which overlap autoimmune disease fine-mapped variants." (PMID 28870212, 2017).
Hydrocephalus (1 paper, 2022). Hydrocephalus is an active distension of the ventricular system of the brain resulting from inadequate passage of CSF from its point of production within the cerebral ventricles to its point of absorption into the systemic circulation. "PRG2, MMP12, and COX4I1 are related to neurological function, and previous studies proved that MMPs were biomakers of BM; however, these proteins were not significantly differed between the hydrocephalus group and healthy groups in our study." (PMID 36052359, 2022).
lung squamous cell carcinoma (1 paper, 2025). "Three compounds (gallic acid, betulinic acid, and caffeic acid) had a significant inhibitory effect on lung squamous cell carcinoma via five biolabels (CPS1, CKM, CPT1B, COX5B, and COX4I1)." (PMID 41502520, 2025).
male infertility (1 paper, 2021). The inability of the male to effect fertilization of an ovum after a specified period of unprotected intercourse. "It has been shown that Cox4i1 (gene encoding the terminal enzyme in the mitochondrial respiratory chain and transcript increased in spermatozoa from stressed rats) is also significantly increased in sperm of obese males mice and could be important for male infertility treatment." (PMID 34071734, 2021).
myelogenous leukemia (1 paper, 2021). "A high-throughput study employing CRISPR death screen searching for OXPHOS essential genes in human myelogenous leukemia K562 cells identified COX4I1 as KO-lethal under conditions when galactose was the sole carbohydrate source." (PMID 33578848, 2021).
oral cancer (1 paper, 2024). "We found that the Y341A L344A mLIR successfully reinstated autophagic substrate (SQSTM1) levels alongside mitochondrial proteins (TOMM20 and COX4I1) when compared to wild-type CLU, signifying the ineffectiveness of the CLU LIR mutant in eliciting cisplatin-induced mitophagy in oral cancer cells." (PMID 38447939, 2024).
tumor (29 papers, 2015 to 2025). "TSPO and COX4I1 are mitochondrial-associated proteins that participate in metabolic processes and oxidative phosphorylation, potentially contributing to the reprogramming of tumor energy metabolism." (PMID 40936684, 2025). "Antibody 15-7, which was derived from a single PC clone in the tumor from patient 15, costained with antibodies specific for the mitochondrial markers, COX4I1 and HSPA9." (PMID 37751306, 2023). "Other proteins of our founded subnetwork, including COX4I1, UQCRC2, ATP5J (ATP5PF), and ENSP00000400168 (ATP5MF-PTCD1), and UQCRQ also play a role in mitochondrial ATP synthesis; they are also involved in tumor initiation, growth, and metastasis." (PMID 38637790, 2024).
cancer (19 papers, 2015 to 2025). A tumor composed of atypical neoplastic, often pleomorphic cells that invade other tissues. "In contrast, our investigation revealed significant overexpression of COX4I1 in blood cancer patients compared to normal blood samples." (PMID 39716856, 2025). "This feedback loop regulating BMI1/COX4i1 expression may be relevant in promoting cancer and maintaining stem cell phenotype." (PMID 25726526, 2015). "The genes encoding the metabolic enzymes for oxidation phosphorylation such as Atp5l, Cox4i1, Cox5a, Cox7a2, Ndufc2, Ndufs4, Sdhd, Uqcrq28 were significantly downregulated in 20(S)/(R)-Rh2E2-treated LLC-1 cancer cells, but not in normal cells." (PMID 32796841, 2020).
infection (10 papers, 2007 to 2026). The state of being infected such as from the introduction of a foreign agent such as serum, vaccine, antigenic substance or organism. "We found that the interaction between Dynll1 and the mitochondrial respiratory chain member Cox4i1 was significantly lowered after infection." (PMID 32041786, 2020). "To test whether Dynll1 exercised its functions through interaction with Cox4i1, we generated Cox4i1 knockout and overexpression DC2.4 cell lines and assessed the functional significance of Cox4i1 during infection." (PMID 32041786, 2020). "Forward and reverse coimmunoprecipitation (Co-IP) assays confirmed that Dynll1 and Cox4i1 could interact and that the extent of the interaction was reduced by infection." (PMID 32041786, 2020). "The expression of Uqcrq, Cox4i1, Ndufb8, Atp6v1g2 and Atp5b involved in oxidative phosphorylation was upregulated in CM-R mice on day 2 post-infection, suggesting that cerebral oxidative metabolism may be stimulated by PbA infection in CM-R mice." (PMID 18062806, 2007). "Because Cox4i1 is known to play an important role in regulating mitochondrial oxygen production, we analyzed the relative content of mitochondrial reactive oxygen species (ROS) during the course of infection using mitochondrial ROS indicator using a dye specific for superoxide." (PMID 32041786, 2020).
neurodegenerative disease (4 papers, 2021 to 2022). A disorder of the central nervous system characterized by gradual and progressive loss of neural tissue and neurologic function. "For example, COX4I1 and COX6B1 enriched in the neurodegenerative disease pathway are two subunits of cytochrome c oxidase, are an integral part of the mitochondrial machinery needed for ATP production in mammalian cells, and are found to be overexpressed when neuronal cells are injured." (PMID 36188472, 2022).
blood cancers (1 paper, 2025). "Analysis of the consortium databases highlighted a pronounced expression and gene dependency on COX4I1 in blood cancers." (PMID 39716856, 2025). "Clinically, we observed selective overexpression of COX4I1 in patients with blood cancers (GENT2 database), indicating a potential involvement of COX4I1 in hematopoietic cancers." (PMID 39716856, 2025).
COX4I1 also shares sentences with these, for which no sentence is quoted: breast carcinoma (6 papers); diabetes (4); Parkinson disease (4); Alzheimer disease (2); Cerebral ischemia (2); colon cancer (2); Huntington disease (2); ischemia (2); Leigh syndrome (2); lung carcinoma (2); melanoma (2); metabolic syndrome (2); prostate carcinoma (2); renal carcinoma (2); Stroke (2); viral infection (2); vitamin D deficiency (2); asthma (1); astrocytoma (1); autism (1); bacterial infection (1); bladder cancer (1); bone marrow failure (1); cardiomyopathy (1); cerebellar ataxia (1); cerebral tumors (1); chronic lymphocytic leukemia (1); colon adenocarcinoma (1); diabetic neuropathy (1); dilated cardiomyopathy (1).
A further 34 diseases each share a sentence with COX4I1 in 1 paper.